ALOX12B (arachidonate 12-lipoxygenase, 12R type)
Diseases named in the same sentence as ALOX12B in open-access papers (continued):
Sharing a sentence is not in itself a finding about the gene and the disease.
tumor (13 papers, 2012 to 2023). "MYH9, GNB1, and ALOX12B were negatively associated with the tumor response, which represented biomarkers of poor outcomes, while HSD17B4 was positively associated with the tumor response." (PMID 36612298, 2023). "After adjusting tumor purity, the expression of ALOX12B was negatively associated with IGFR1, AKT1, MTOR, and EIF4EBP1, and the same correlation could also be observed in SPRR1A." (PMID 35768785, 2022). "Therefore, the integrated roles of ALOX12B in the tumor microenvironment (CD8+ T cell, CAFs, regulatory T cells, myeloid-derived suppressor cells and so on) merit further investigation." (PMID 35768785, 2022). "ALOX12B, an immunosuppressive factor, can inhibit immunity and promote tumor progression." (PMID 36199579, 2022). "Therefore, poor prognosis patients with low ALOX12B expression had high infiltration of CAFs surrounding tumor cells, and rapamycin or everolimus may provide survival benefits by inhibiting mTOR signaling." (PMID 35768785, 2022). "The expression levels of ALOX12B, GPX2, DDIT4, GDF15, and RRM2 in tumor tissues were significantly higher than those in the normal lung tissues." (PMID 34307361, 2021). "IHC results showed that ALOX12B and PTGIS proteins presented low expression in groups of OSCC and non-tumor tissues." (PMID 30532780, 2018). "Four ferroptosis driver genes FLT3, ALOX12B, ALOX15, and VDAC2, had a low CNV, and four ferroptosis suppressor genes ACSL3, CISD1, FANCD2, and SLC3A2, had a high CNV, indicating that ferroptosis was inhibited in tumor development." (PMID 34434214, 2021). "Arachidonate 12-lipoxygenase, 12R type (ALOX12B) can convert arachidonic acids to 12R-hydroxyeicosatetraenoic acids 8 and is responsible for immune activity blocking the uptake of apoptotic cells through inflammatory monocytes which reduces antigen presentation to T cells in tumor." (PMID 37221577, 2023). "Results demonstrated an invariably unmethylated (WNT10B) or methylated (TUB, ALOX12B, SLC6A11) status of the normal samples (data not shown) as compared to the variable levels of methylation observed in tumor cells." (PMID 22950745, 2012).
cancer (4 papers, 2022 to 2025). A tumor composed of atypical neoplastic, often pleomorphic cells that invade other tissues. "Future research should focus on functional characterization of VUS in genes like SIL1, SNX14, and ALOX12B to elucidate their potential role in cancer pathways." (PMID 41229501, 2025). "Downregulated expression of ALOX12B or SPRR1A was associated with poor survival rate and advanced cancer stages." (PMID 35768785, 2022). "In the HPV- HNSCC TCGA database (TIMER2.0 online database), the xCell, EPIC, MCP-counter, and TIDE algorithms showed that downregulation of both hub genes (ALOX12B and SPRR1A) were correlated with increased cancer-associated fibroblasts (CAFs)." (PMID 35768785, 2022). "Elevated ALOX12B expression was also observed in the earlier cancer stage in the GSE65858 and GSE41613 data sets (P = 0.024 and P = 0.028, respectively)." (PMID 35768785, 2022). "Notably, the expression of ALOX12B and SPRR1A were negatively correlated with cancer-associated fibroblasts (CAFs) infiltration and CAFs downstream effectors." (PMID 35768785, 2022). "SPRR1A and ALOX12B downregulation was observed in HPV16- HNSCC patients at advanced cancer stage." (PMID 35768785, 2022).
cutaneous disorder (2 papers, 2016 to 2025). "Although traditionally considered a cutaneous disorder, the systemic immunological implications of ALOX12B deficiency remain poorly understood." (PMID 41346588, 2025). "It is interesting that many of the changes in gene expression found in HaCaT-IKKα skin equivalents are relative to genes involved in the development of different skin disorders (CNFN, CDSN, TGM1, ALOX12B, etc)." (PMID 27732959, 2016).
adenocarcinoma (1 paper, 2023). A common cancer characterized by the presence of malignant glandular cells. "In 230 patients with adenocarcinoma from the TCGA cohort, higher expressions of MYH9, GNB1, and ALOX12B were associated with poor overall survival outcomes, while higher expression of HSD17B4 was associated with better survival outcomes." (PMID 36612298, 2023).
infection (1 paper, 2025). The state of being infected such as from the introduction of a foreign agent such as serum, vaccine, antigenic substance or organism. "However, expression of Alox12, Alox12e, Alox8, Alox12b, Il13rα1, Il4rα, Il2rg, and Il13 were not altered following Hpb infection." (PMID 40490052, 2025).
inherited diseases (1 paper, 2020). "Similar to other genes associated with inherited diseases, large deletions have been found among the ALOX12B and CYP4F22 disease alleles." (PMID 33255364, 2020).
ALOX12B also shares sentences with these, for which no sentence is quoted: congenital ichthyosis (3 papers); neurological disorders (2); autosomal recessive congenital ichthyosis-2 (1); autosomal-recessive exfoliative ichthyosis (1); bone tumor (1); colorectal cancer (1); congenital ichthyosiform erythroderma (1); dermatitis (1); eczema (1); erythroderma (1); esophageal squamous cell carcinoma (1); glioma (1); Harlequin ichthyosis (1); lamellar ichthyosis (1); lung adenocarcinoma (1); lymphoma (1); microtia (1); Netherton syndrome (1); osteoporosis (1); osteosarcoma (1); palmoplantar keratoderma (1); Pruritus (1); stenosis (1).